SIRT2 (sirtuin 2)
Diseases named in the same sentence as SIRT2 in open-access papers (continued):
Sharing a sentence is not in itself a finding about the gene and the disease.
migraine (1 paper, 2025). "There is no direct evidence regarding the involvement of sirtuins other than SIRT1 or SIRT2 in migraine, but reports on the role of other sirtuins in neurological disorders justify further research on this subject." (PMID 40724883, 2025). "NQO1 plays a vital role in various aspects of cellular functioning, including antioxidant defense, and may thus link migraine with oxidative stress through SIRT2." (PMID 40724883, 2025). "Therefore, neuropathic pain and migraine may share some common pathways in their pathogenesis, potentially involving the interaction between SIRT2 and NRF2." (PMID 40724883, 2025). "The upregulation of SIRT2 restores the expression of the NFE2L2 gene, which encodes NRF2 and NQO1, while also decreasing oxidative stress in the injured spinal cord of rats, which leads to improvements in thermal hyperalgesia and mechanical allodynia, highlighting the potential of SIRT2 in migraine." (PMID 40724883, 2025).
minimal change disease (1 paper, 2023). "Immunohistochemistry also studies revealed a marked decrease in the intensity of SIRT2 staining in kidney sections from patients with DKD compared to those of the control group (patients diagnosed with minimal change disease)." (PMID 37777567, 2023).
multiple myeloma (1 paper, 2024). "Furthermore, decreased SIRT2 and SIRT3 concentrations have been correlated with disease progression and increased redox imbalance in multiple myeloma patients." (PMID 39727710, 2024).
myeloid leukemia (1 paper, 2013). A clonal proliferation of myeloid cells and their precursors in the bone marrow, peripheral blood, and spleen. "Although a previous report shows that knockdown or inhibition of Sirt2 with AC93253 in myeloid leukemia cells activates GSK3β through decreased Ser9 phosphorylation and prevents aberrant proliferation, little is known about the role of Sirt2 and GSK3β in ESCs." (PMID 24204656, 2013).
Pain (1 paper, 2022). An unpleasant sensory and emotional experience associated with actual or potential tissue damage, or described in terms of such damage. "Therefore, high levels of SIRT2 in plasma could be a biomarker for lower microtubule acetylation associated with impaired axonal transport in peripheral neurons, and thus be causally involved in neuropathic pain." (PMID 35408848, 2022).
pancreatic adenocarcinoma (1 paper, 2016). "This is consistent with a tumor suppressor role of SIRT2 in the pancreas, which is also in line with lower SIRT2 mRNA levels detected in pancreatic adenocarcinoma compared to normal tissue." (PMID 27637077, 2016).
polycystic ovary syndrome (1 paper, 2025). A disorder that manifests as multiple cysts on the ovaries. "In polycystic ovary syndrome (PCOS), overexpression of DKK1 reduced the apoptosis rate of granulosa cells; moreover, overactivation of SIRT2 and increased deacetylation of DKK1 were detected in cells from PCOS rats." (PMID 40664665, 2025).
postmenopausal osteoporosis (1 paper, 2023). Metabolic disorder associated with fractures of the femoral neck, vertebrae, and distal forearm. "Our results show that hepatocyte-specific SIRT2 deficiency (SIRT2-KOhep) markedly abolishes bone loss in aged and postmenopausal osteoporosis mouse models." (PMID 37188819, 2023).
renal carcinoma (1 paper, 2022). A carcinoma arising from the epithelium of the renal parenchyma or the renal pelvis. "Renal cancer cells express high levels of SIRT2, which is associated with a poorer prognosis for patients." (PMID 36844923, 2022).
sarcoma (1 paper, 2014). A usually aggressive malignant neoplasm of the soft tissue or bone. "We found that the pharmacological inhibition of SIRT1 and SIRT2 with tenovin-6 effectively inhibited the proliferation of seven pediatric sarcoma cell lines at concentrations between 2 and 5 μM." (PMID 25341037, 2014). "Using siRNA to knock down SIRT1 and SIRT2 expression, we demonstrated that SIRT1 and SIRT2 expression is crucial for the survival of sarcoma cells." (PMID 25341037, 2014). "To prove whether sirtuins are essential to sarcoma cell growth, we knocked down SIRT1 and SIRT2 in RD cells using a cocktail of four different siRNAs for each sirtuin to avoid off-target effects, and followed cell proliferation for 120 h." (PMID 25341037, 2014).
sarcopenia (1 paper, 2024). Progressive decline in muscle mass due to aging which results in decreased functional capacity of muscles. "However, the roles of SIRT2 in sarcopenia seemed paradoxical: the causal effects of SIRT2 on hand grip strength were protective while on AWCU10 was negative." (PMID 39229276, 2024). "In this study, the potential upstream cell phenotypes were identified and the downstream effects of SIRT2 on sarcopenia were also enriched." (PMID 39229276, 2024). "The protective causal effects of EM DN (CD4- CD8-) %DN on sarcopenia were also possible via SIRT2, due to the negative causal association of SIRT2 with AWCU10." (PMID 39229276, 2024). "In this study, higher EM DN (CD4- CD8-) %DN was proven to be causally associated with higher levels of IL-17A, higher scores of AALM, lower levels of SIRT2, LIF-R, and DNER, and lower risk of poor hand grip strength (EWGSOP), which might be protective causal factors of sarcopenia." (PMID 39229276, 2024).
skin cancer (1 paper, 2017). "In human skin cancer cells, SIRT2 is downregulated and deficiency of SIRT2 was shown to promote tumor growth in mice." (PMID 29179522, 2017).
skin melanoma (1 paper, 2021). "The roles of intracellular SIRT2 as either a tumor suppressor or oncogene have been reported in several cancers including liver, breast, brain, and skin melanoma." (PMID 34155309, 2021).
spinal cord disorder (1 paper, 2025). A disease involving the spinal cord. "Together, our results uncover SIRT2 as a key regulator of spinal cord neurogenesis and position it as a promising target for strategies aimed at neural repair in spinal cord disorders." (PMID 41154588, 2025).
squamous cell carcinoma (1 paper, 2023). A carcinoma arising from squamous epithelial cells. "Another study on squamous cell carcinoma (SCC) found lower levels of SIRT2 in tumors and that SIRT2 deletion enhances the risk of carcinogenesis." (PMID 36993812, 2023).
tongue cancer (1 paper, 2022). A malignant neoplasm affecting the tongue. "Importantly, NAD+ supplementation in cancer cells activated SIRT2 but did not inhibit cisplatin-induced cytotoxicity against lung and tongue cancer cells." (PMID 35875690, 2022).
type 1 diabetes mellitus (1 paper, 2020). A chronic condition characterized by minimal or absent production of insulin by the pancreas. "The expression and activity of Sirt1, Sirt2, Sirt3, and Sirt5 is reduced in a streptozotocin- (STZ-) induced type 1 diabetes mellitus (T1DM) model, while the level of Sirt3 is increased in a high-fructose diet-induced T2DM model." (PMID 32256959, 2020).
cancer (209 papers, 2006 to 2026). A tumor composed of atypical neoplastic, often pleomorphic cells that invade other tissues. "SIRT1 and SIRT2 have emerged as promising targets for therapeutic interventions in various diseases associated with gut dysbiosis, including cancer, neurodegenerative disorders, and metabolic conditions." (PMID 40136715, 2025). "SIRT2 also plays a role in metabolic pathways, affecting energy metabolism and genome stability, and it has been implicated in the pathogenesis of cancer and neurodegenerative diseases." (PMID 40710366, 2025). "Recent findings highlight the crucial role of SIRT2 in regulating pathways linked to cancer, particularly those involved in tumor growth and metastasis." (PMID 41428704, 2025). "Taken together, our data demonstrate that at least five cancer-derived SIRT2 mutations reduce the capability of SIRT2 to promote OGG1 transcription to enhance BER efficiency, thereby contributing to tumorigenesis." (PMID 38554113, 2024). "To determine the functional consequences of SIRT2-mediated regulation of OGG1 transcription, we identified 37 cancer-associated mutations in SIRT2 through data mining using the TCGA database." (PMID 38554113, 2024). "We also characterized 37 cancer-derived SIRT2 mutants and found that 5 exhibited the loss of the stimulatory effects on OGG1 transcription." (PMID 38554113, 2024). "In some cancers, such as gliomas, the downregulation of SIRT2 is associated with increased malignancy, suggesting its crucial role in cancer development." (PMID 39682281, 2024). "Dysregulation ofboth tubulin deacetylases sirtuin 2(Sirt2) andthe histone deacetylase 6 (HDAC6) has been associated with the pathogenesisof cancer and neurodegeneration, thus making these two enzymes promisingtargets for pharmaceutical intervention." (PMID 37902787, 2023). "SIRT2 is implicated in different human diseases, including neurodegenerative diseases, cancer, and infections." (PMID 38005376, 2023). "Resveratrol, an activator for longevity regulatory genes-sirtuin family (SIRTs) and Sirtuin 2 (SIRT2) is an important factor of SIRTs which demonstrated biological function in cancers, but the underlying mechanism is unrevealed." (PMID 36844923, 2022). "SIRT2 is thought to affect carcinogenesis in a context-dependent manner, affecting epigenetic pathways implicated in cancer initiation, development, and progression." (PMID 35845599, 2022). "It has been noticed that SIRT2 can act as a tumor suppressor, but only in early BC carcinogenesis; inversely, in advanced stages of cancer, overexpression of SIRT2 is associated with a more aggressive phenotype." (PMID 35406775, 2022). "Metabolic pathway reprogramming is a hallmark of cancer, and SIRT2 can affect tumour progression through metabolic pathways." (PMID 36101744, 2022). "Another important finding was the correlation between the level of SIRT2 expression and the level of cancer-associated immune infiltration, particularly in LUAD." (PMID 36844923, 2022). "Currently, the literature supports diverging functions for SIRT2 in tumorigenesis, in a context-dependent manner, that act to modify epigenetic pathways implicated in cancer’s initiation, promotion, and progression." (PMID 34155309, 2021). "Although Sirt2 suppresses inflammation, stimulate the pentose phosphate pathway, it is also associated with neurodegenerative and metabolic diseases and cancer." (PMID 33806577, 2021). "It is assumed that repression of SIRT2 is associated, at least in part, with miR-212-5p-mediated cancer cell progression, as supported by Du." (PMID 34943825, 2021). "The tubulin deacetylase SIRT2 has also been associated with autophagy regulation in several cancer cell lines, although its impact on cancer autophagy is less well understood, in comparison with HDAC6." (PMID 35008169, 2021). "Currently, there is growing evidence that abnormal expression of SIRT2 is primarily associated with two human diseases, neurologic diseases, and cancer." (PMID 33014852, 2020).
cancer (continued). "Dysregulation of SIRT2 activity, abundance or nuclear levels have been associated with poor cancer prognosis and heightened metastasis." (PMID 32042025, 2020). "SIRT2 is involved in multiple cellular functions, including genomic integrity, cell growth, differentiation, and energy metabolism, and reduced SIRT2 activity has been implicated in cancer, neurodegeneration and metabolic diseases." (PMID 30972029, 2019). "The different cellular localization of SIRT2 is responsible for different biological downstream effects causing many pathologies including cancer." (PMID 30761005, 2019). "Support for this idea comes from studies using SIRT2, an antitumor and lifespan-extending protein, which activates the APC by deacetylating CDC20 and CDH1; SIRT2-deficient mice exhibited higher levels of cancer and elevated levels of APC substrates." (PMID 29954095, 2018). "Our extensive analysis, including automated intensity scoring, suggests SIRT2 loss correlates with aggressive cancer and occurs early in prostate tumorigenesis." (PMID 29262808, 2017). "Dysregulated SIRT2 activity has been associated with aging, cancer, metabolic disorders and neurodegeneration." (PMID 28445509, 2017). "In patients with stage 1 cancer, significant association was only found between SIRT2 and OS (n = 67)." (PMID 29088792, 2017). "The human isotype Sirt2 has been implicated in the pathogenesis of cancer, inflammation and neurodegeneration, which makes the modulation of Sirt2 activity a promising strategy for pharmaceutical intervention." (PMID 25672491, 2015). "Sirtuin 1 (SIRT1) and sirtuin 2 (SIRT2) are NAD+-dependent protein deacetylases involved in the regulation of key cancer-associated genes." (PMID 25915617, 2015). "Salermide is an inhibitor of Sirt1 and Sirt2 that causes apoptotic tumor-specific cell death in a variety of human cancer cell lines." (PMID 24069483, 2013). "Thus, irregular SIRT2 activity has been associated with the onset and dissemination of cancer diseases." (PMID 41428704, 2025). "Notably, in this work, we analyzed 37 cancer-associated SIRT2 mutants, and only five of them exhibited loss of the stimulatory effect on OGG1 promoter activity and mRNA expression." (PMID 38554113, 2024). "In a slew of studies, sirtuin 2 (SIRT2) has been linked to cancer pathogenesis." (PMID 36750593, 2023). "Different forms of cancer have been associated with dysregulation of SIRT2 activity." (PMID 36750593, 2023). "Therefore, single CpG methylation patterns of SIRT2 can be a potential biomarker for cancer risk assessment." (PMID 35406775, 2022). "Currently, there is increasing evidence that the aberrant expression of SIRT2 may be associated with human diseases, neurological disorders, and cancer." (PMID 35493297, 2022). "We investigated the mRNA and protein levels of SIRT2 in a variety of cancers and the potential role for clinical prognosis, as well as analysed the association between the gene and immune infiltration in various cancers." (PMID 36844923, 2022). "Indeed, loss of SIRT2 altered PKM2 activity and reprogrammed glycolytic metabolism in cancer cells, which was associated with increased tumorigenesis in Sirt2–/– mice." (PMID 33014852, 2020). "SIRT2 is a member of sirtuin family and is associated with cell growth in various cancers." (PMID 28514749, 2017). "SIRT2 is implicated in the pathology of cancer and neurodegenerative diseases." (PMID 27875273, 2016). "Notably, it has been revealed that SIRT2 is also linked with cancer metabolism and promotes tumor growth." (PMID 27916001, 2016). "The anti-cancer activity of SIRT2 inhibitors was shown to occur simultaneous to cancer cell inhibition but whether this is symptom or causes remains to be established." (PMID 23382805, 2013). "In addition, in vertebrate, SIRT2-deficient cells are susceptible to apoptosis when treated with anti-cancer reagents such as staurosporine or cisplatin." (PMID 23460888, 2013).
cancer (continued). "Consequently, further research into the molecular associations between the cytoskeleton and nucleus following SIRT2 inhibition could yield valuable insights for reducing cancer cell invasiveness." (PMID 39682770, 2024). "Since cancer-associated mutations often cause rapid protein degradation and these mutations apparently affect protein functions, we first examined whether these mutations affect the protein level of SIRT2." (PMID 38554113, 2024). "Sirtuin 1 (SIRT1) and Sirtuin 2 (SIRT2) are NAD+-dependent deacetylases that regulate cancer metabolic stress, exerting their effects primarily through post-translational modification of metabolic enzymes and transcription factors." (PMID 41800243, 2026). "This review summarizes recent advances in understanding how SIRT1 and SIRT2 coordinate tumor metabolism and discusses therapeutic strategies that target their regulatory balance to reprogram cancer metabolism." (PMID 41800243, 2026). "The human NAD (+)-dependent deacetylase silent information regulator isoform 2 (SIRT2) is the cytoplasm-localized member of the sirtuin family, which has received increasing attention for its potential roles in cancer diagnosis and therapy." (PMID 42009830, 2026). "When researchers inhibited SIRT2 activity, the inhibitory effect of resveratrol on GSC proliferation was significantly reduced, indicating SIRT2’s involvement in how resveratrol affects the growth of these cancer cells." (PMID 40710366, 2025). "The inhibition of sirtuin 2 (SIRT2) induces the acetylation and proteasomal degradation of fibrinogen-like protein 1, thus promoting cancer immunotherapy." (PMID 40765819, 2025). "This research highlights the promising therapeutic potential of targeting SIRT2 in cancer treatment by utilizing fungal secondary metabolites as novel inhibitors." (PMID 41428704, 2025). "Therapeutically, SIRT2 would be an attractive target for augmenting innate antitumor immunity, particularly in cancer types where NK cell dysfunction is an etiopathogenic factor leading to immune escape." (PMID 41425553, 2025). "Studies have shown that downregulation of SIRT2 can induce apoptosis in cancer cells and mediate oxidative stress-induced apoptosis." (PMID 40317067, 2025). "The selectivity pocket is a key binding site for inhibitorsofthe NAD+-dependent lysine deacylase Sirtuin 2 (Sirt2),a promising drug target in diseases like cancer." (PMID 40390200, 2025). "This study provides insights into the interplay between SIRT2, HSC70, and CMA, with potential implications for diseases linked to proteostasis dysregulation, including neurodegenerative disorders and cancer." (PMID 41255949, 2025). "IBC affects a wide spectrum of biological functions, including the activity of the NAD+-dependent deacetylase Sirtuin 2 and shows antitumor activity against drug-resistant cancers." (PMID 39887032, 2025). "The in silico docking studies identified that compound 22 is able to interact with human SIRT2 and EGFR proteins (often found to be mutated or overexpressed in various cancer cell lines) with promising antiproliferative activity." (PMID 40430551, 2025). "SIRT2 regulates important physiological functions for the cell and plays a role in many cancers and neurodegenerative diseases." (PMID 39808389, 2025). "For instance, in osteosarcoma, SIRT2 deacetylates the epithelial‐mesenchymal transition (EMT)‐associated factor Snail, thus inhibiting its degradation and promoting cancer cell proliferation, invasion, and metastasis." (PMID 39215785, 2025). "The new compounds were tested against SIRT1 and SIRT2 and evaluated for their cytotoxic activities against a panel of nine cancer cell lines." (PMID 38794171, 2024). "In vitro assays pointed to 5a as a promising anticancer agent to be optimized for the treatment of SCC and other malignancies where SIRT2 plays a prominent role in cancer development and progression." (PMID 39456864, 2024).